RN7SKP78 (RN7SK pseudogene 78)
Gene: Miscellaneous RNA gene on chromosome 10 (6,149,623 to 6,149,940, forward strand). Ensembl gene ENSG00000201581.
Homologues: Orthologues: chimpanzee 7SK (93% identical). Paralogues in human: 7SK (76% identical), RN7SKP71 (75% identical), RN7SKP124 (75% identical), RN7SKP176 (75% identical), RN7SKP180 (75% identical), RN7SKP25 (75% identical), RN7SKP79 (75% identical), RN7SKP6 (74% identical), RN7SKP131 (74% identical), RN7SKP47 (74% identical), RN7SKP63 (74% identical), RN7SKP9 (74% identical), and 284 more.